CTCF (CCCTC-binding factor)
Diseases named in the same sentence as CTCF in open-access papers (continued):
Sharing a sentence is not in itself a finding about the gene and the disease.
cancer (continued). "Moreover, the putative heterodimerization of CTCF and BORIS at the 2xCTSes have been shown to be involved in transcriptional program of cancer cells and activation of testes-specific genes in cancer." (PMID 34158481, 2021). "Unlike the situation in cancer cells where cohesin counteracts super-enhancer interaction, in ESCs, cohesin was required for super-enhancer interactions, and this also relied on CTCF." (PMID 31968256, 2020). "The binding of CTCF to the first exon of the hTERT gene was reported to suppress its expression in telomerase‐negative cells but not in cancer cells in a DNA methylation‐dependent manner." (PMID 31736271, 2020). "This study clarifies the relative and combined contribution of CTCF and CTCFL to chromosome organization and transcription, with direct implications for understanding how their co-expression deregulates transcription in cancer." (PMID 32393311, 2020). "Further, we found six genes—FOXL2, TNFAIP3, CHD1L, HRAS, KIT, CTCF—that occurred in 12 cases that are not on the top 20 list of any of the four common cancers used for comparison." (PMID 32570879, 2020). "As CTCF was known to induce DNA looping and is enriched at TAD boundaries, we then interrogated the relationship between altered CTCF occupancy and chromatin conformation in cancer." (PMID 32933554, 2020). "The average Ki67‐LI increased from 2.1 ± 0.05 in cancers lacking CTCF expression to 3.20 ± 0.06 in cancers with low and to 3.42 ± 0.09 in cancers with high CTCF levels (P < 0.0001)." (PMID 31736271, 2020). "This study clarifies the unique and combined contribution of CTCF and CTCFL to chromosome organization and transcription, with direct implications for understanding how their co-expression deregulates transcription in cancer." (PMID 32393311, 2020). "The level of immunostaining was typically higher in cancers than in normal prostate glands, the latter of which showed mostly negative and only sometimes weak CTCF expression." (PMID 31736271, 2020). "Overall, although TADs are highly conserved between cell types and are often delimited by CTCF motifs, our results show the relationship of TAD boundaries with cancer-related transcription factors rather than with CTCF." (PMID 30894186, 2019). "Two transcriptional regulators, including RUNX1 and CTCF, were not identified as driver cancer genes." (PMID 29485617, 2018). "Although methylation of exon 1 region is the most prevalent mechanism to regulate hTERT in tumor cells and tissues, it is found that in some cancer cells, the expression of BORIS prevents the repressive effects of CTCF on hTERT gene, and permits its transcription." (PMID 30323717, 2018). "This looping was not limited to cancer cells, because examination of enhancer and promoter-capture Hi-C data in a variety of normal cell types that express MYC revealed that cell-type-specific enhancers do indeed loop to the MYC proximal CTCF site." (PMID 29641996, 2018). "To understand the global patterns of selective DNA occupancy by co-expressed CTCF and BORIS, we performed comprehensive ChIP-seq and ChIP-reChIP-seq analyses of both proteins in several human somatic cancer cell lines as well as mouse post-meiotic round spermatids." (PMID 29077515, 2018). "Furthermore, genes reported to promote tumor metastasis in various cancers, including SRC, TGFB1 and MMP9, were upregulated by CTCF." (PMID 28977939, 2017). "Thus, from the standpoint of cancer biology, it was important to characterize repeats bound by both CTCF and BORIS (CTCF and BORIS repeats), especially as they outnumbered other classes." (PMID 27588042, 2016).
cancer (continued). "Thus, evidently, CTCF and BORIS heterodimeric complexes are not only common in cancer cells of different origins, but can be formed upon induction of BORIS expression in BORIS-negative cells." (PMID 26268681, 2015). "CTCF is ubiquitously expressed in all types of cells, while BORIS expression is normally restricted to germ cells and could be aberrantly activated in cancers." (PMID 26268681, 2015). "Similarly to cancer cells, all three marks of active transcription were significantly enriched at BORIS-bound regions compared with CTCF-only bound regions, signifying the involvement of 2xCTSes in germline transcription regulation." (PMID 26268681, 2015). "The pattern of CTCF and BORIS occupancy across different cancer cell lines raises the question of whether CTCF and BORIS heterodimerization is preprogrammed in the genome sequence by the 2xCTSes." (PMID 26268681, 2015). "Similarly to GAL3ST1, PRAME and FOXA3 genes were also silent under CTCF occupancy, but were activated upon CTCF and BORIS co-binding in both cancer and germ cells." (PMID 26268681, 2015). "We found that BORIS, together with CTCF, occupies as much as one-third of CTSes and “sidesteps” the remaining two-thirds of CTSes regardless of the origin of cancer cells." (PMID 26268681, 2015). "This conclusion is primarily based on our finding that the genome-wide occupancy of 1xCTSes and 2xCTSes by CTCF and BORIS in cancer cells largely recapitulates their binding profile in germ cells, at least for the subset of binding regions that are conserved between mice and humans." (PMID 26268681, 2015). "In cancer, this putative mechanism would not occur due to the absence of CTCF in its DNA-binding site via a methylation-sensitive mechanism." (PMID 26443201, 2015). "The fact that CTCF and BORIS share a virtually identical DNA binding domain and are co-expressed in at least two environments, in germ and cancer cells, raises the question of whether they bind competitively or cooperatively at a given DNA sequence." (PMID 26268681, 2015). "The genomic binding patterns of CTCF and BORIS in cancer cells suggest that the heterodimerization between these two proteins could also be characteristic for germ cells." (PMID 26268681, 2015). "To clarify whether CTCF could regulate AATK expression, we transfected CTCF in HeLa, A549 and H322 cancer cells." (PMID 25352953, 2014). "To address this question, we selected the promoters, CTCF sites, and enhancers that were defined in normal cells (ChromHMM; HMEC and PrEC) and then characterized the epigenetic changes that occur at these precise genomic regions in cancer cells (MCF7 and PC3)." (PMID 24916973, 2014). "Recent publications indicate that reciprocal binding of the transcriptional factors, CTCF or BORIS, to a promoter sequence may be a general mechanism of regulation of the cancer-testis (CT) specific genes, expression of which is restricted to male germ cells." (PMID 17406683, 2007). "However, 50 transcription factors displayed similar interactions with SWI/SNF in the two cancer types, such as several zinc-finger transcription factors (ZNF512, ZNF598, ZNF609, ZNF687, and ZNF709), CTCF, ELF2, and YBX1, indicating shared gene regulation networks." (PMID 40988026, 2025). "CCCTC-binding factor (CTCF), a DNA binding protein, exhibits specific binding patterns in the genome of cancer cells and has a non-canonical function to facilitate oncogenic transcription programs by cooperating with transcription factors bound at flanking distal regions." (PMID 38397134, 2024). "However, the mechanisms by which CTCF and CTCFL interact to regulate the gene transcription in the testis and cancer, and whether they alter 3D chromatin architecture, remain poorly understood." (PMID 39430552, 2024). "Thus, as was previously reported in cancer cells with LOI, CTCF-orchestrated intrachromosomal looping may be essential for maintaining normal imprinting of IGF2 in decidual tissues." (PMID 36231092, 2022).
cancer (continued). "The discrepancy with other published studies regarding CTCF nuclear localization is most likely due to the use of different cell types, such as immortalized cancer cell lines, or embryonic stem cells, where we also did not detect CTCF enrichment at SC-35 nuclear speckles." (PMID 33411704, 2021). "The exact degree of functional integration of CTCF–BORIS heterodimers currently remains unknown, as a systematic genetic analysis has yet to be performed in a normal developmental process—i.e., outside of cancer states." (PMID 34158481, 2021). "GSEA indicated that multiple cancer signaling pathways (mTOR pathway, GSK3 pathway, EIF4 pathway, CHREBP2 pathway, MET pathway, NFAT pathway, FAS pathway, EDG1 pathway, AKT pathway, and CTCF pathway) were differentially enriched in YTHDF2 increased expression phenotype." (PMID 33102202, 2020). "However, unlike enhancer and chromatin contact profiles, which show dramatic differences between normal and cancer cells, the CTCF profiles were not that different." (PMID 31515496, 2019). "CTCF is well known to cooperate with cohesin in regulating genome architecture, and increased expression of BORIS in previously BORIS-negative cancer cells could thus rewire genome architecture by replacing one or two CTCF molecules at some of its target regions." (PMID 29077515, 2018). "However the mechanism by which CTCF haploinsufficiency contributes to cancer development is not well understood." (PMID 28319062, 2017). "The investigation of BORIS and CTCF binding to DNA repeats in the K562 cancer cells dependent on BORIS for self-renewal by ChIP-chip and ChIP-seq revealed three classes of occupancy by these proteins: elements cohabited by BORIS and CTCF, CTCF-only bound, or BORIS-only bound." (PMID 27588042, 2016). "Importantly, in cancer cell lines, the lack of CTCF regulation on the XAF1 promoter via methylation on its cognate binding site partially blocks its transcriptional responsiveness to two well-known transcriptional activators, TNF-α or IFN-α." (PMID 26443201, 2015). "For this purpose, we developed a large set of anti-CTCF and anti-BORIS mouse monoclonal antibodies, thoroughly validated by immunoblotting, electrophoretic mobility shift assay (EMSA), and ChIP-seq for both BORIS-positive cancer cells and BORIS-negative normal human dermal fibroblasts (NHDFs)." (PMID 26268681, 2015). "Furthermore, CTCF unbound insulator sequence allowed encroachment of methylation and heterochromatin structure into downstream RASSF1A promoter which hindered its transcriptional activity in H1299 cancer cell." (PMID 20877461, 2010). "BORIS can interfere with CTCF functions in cancer cells not just by virtue of having the identical ZF binding domain and overlapping DNA binding specificity, but also due to its distinct amino- and carboxy-termini that likely confer a discrete set of molecular functions." (PMID 21079786, 2010). "Thus, it is not surprising that deregulation of CTCF has been observed in many human cancer types." (PMID 31736271, 2020). "Also, although direct pathway or gene ontology analysis on all genes near these identified lost/gained CTCF sites did not yield much insights into cancer functions, we did observe a clear pattern of differential gene expression associated with CTCF binding alteration." (PMID 32933554, 2020). "We observed a significant inverse correlation between CTCF and IL6 gene expression levels in BrCa samples from patients with disease-free survival but not in those with cancer recurrence." (PMID 40143084, 2025). "An inverse correlation between CTCF and IL6 expression levels was seen in disease-free survival BrCa patients but not in patients who experienced cancer recurrence." (PMID 40143084, 2025). "CTCF itself is not sufficient for such conversion but serves as a precise landmark for BORIS to bind and reprogram CTCF sites in germ and cancer cells." (PMID 38297316, 2024).
cancer (continued). "There is current research going on in this regard, and without a doubt, the study of the interplay between CTCF and BORIS in cancer will help to understand CTCF’s role in chromatin organization and other epigenetic processes." (PMID 37408191, 2023). "While the emCpGs harbour enriched binding sites for their specific emTFs, the non-correlated CpGs shared a binding signatures for SP1, CTCF, NRF1, GABPA, KLF9, and YY1 providing a protective effect against de novo methylation across cancer types." (PMID 35440061, 2022). "In contrast, the protein level of CTCF was not markedly changed in LFS cell lines but is significantly up-regulated in MCF7 and IMR32 cancer cell lines in comparison to normal cell, HS27." (PMID 27542210, 2016). "The BORIS-only repeats, where BORIS binds without the equivalent presence of CTCF, are the most revealing with respect to BORIS biology in cancer cells, as they are directly involved in the transcriptional regulation of the non-repeated part of the genome." (PMID 27588042, 2016). "Unlike its widely expressed paralog CTCF, BORIS is repressed in normal tissues and expressed only in the testis and in several types of human cancers, including lung, head and neck, breast, skin, and urinary cancers." (PMID 22792300, 2012). "Unlike CTCF, BORIS expression has been reported only in the testis and certain malignancies, leading to its classification as a “cancer-testis” antigen." (PMID 21811597, 2011). "ChIP-PCR results indicated that CTCF protein bound to the insulator located between the RASSF1A and BLU loci in the IMR90 normal cells but not the H1299, A549, and CL1-0 cancer cells." (PMID 20877461, 2010). "Finally, we found a statistically significant inverse correlation between CTCF and IL6 expression levels in BrCa tissues from patients with good prognoses, but not in those with cancer recurrence." (PMID 40143084, 2025). "CTCF paralogue CTCFL is normally not expressed in adult tissues, besides specific stages of spermatogenesis, due to promoter methylation of its gene, but is re-expressed in some cancer cases." (PMID 30275357, 2018).
tumor (168 papers, 2004 to 2026). "Among the eight significant mutated genes, CDK12, CTNNB1, and MLH1 were tested in both tumor and blood, whereas CTCF, IGF1R, IKBKE, QKI, and TIPARP were only tested in tDNA." (PMID 40227722, 2025). "Specifically, this is the first time that we found that SE‐lncRNA SUCLG2‐AS1 is linked to the tumour metastasis driver gene CTCF, contributing to SOX2 through the loop regulation ability to form RNA/DNA/DNA triplexes in NPC." (PMID 37658588, 2023). "By analyzing the association between RBM14 expression and EP300 and YY1 levels using TIMER database, we found that RBM14 expression was strongly associated with the expression of EP300, CBP, and CTCF in various types of tumor tissues." (PMID 37060064, 2023). "Hemizygous CTCF mice however, are viable and fertile, yet are predisposed to both spontaneous and induced tumor incidence, with global DNA methylation changes and deregulated gene expression patterns across tissues." (PMID 37324587, 2023). "In NB cells, hnRNPU interacts with CTCF resulting in transcriptional alteration of genes associated with tumor progression." (PMID 35954396, 2022). "Although not lethal, the loss of heterozygosity at the CTCF locus is also detrimental to cellular homeostasis, and CTCF appears to act as an haploinsufficent tumor suppressor gene, with its loss impacting hematopoietic tumor initiation in CTCF hemizygous mice." (PMID 36037342, 2022). "hnRNPU interacts with CTCF resulting in transcriptional alteration of genes associated with tumor progression." (PMID 35954396, 2022). "We divided tumours according to CTCF (mutated/deleted) and histone 1 cluster (deleted) status, excluding tumours variant for both." (PMID 34753926, 2021). "Loss of the locus that contains the CTCF gene is frequently detected in breast and prostate cancer, which underlines its tumor suppressor activity." (PMID 34065345, 2021). "CTCF expression was significantly associated with advanced pathological tumor stage, high Gleason grade (P < 0.0001 each), nodal metastasis (P = 0.0122), and early biochemical recurrence (P < 0.0001)." (PMID 31736271, 2020). "Although these data indicated Ctcf behaved as a tumor suppressor gene, which was also supported by somatic mutation burden of CTCF in a recent human pan-cancer study, contradictory results were seen in other models regarding the CTCF/MYC regulation axis." (PMID 31127282, 2019). "Lastly, despite the fact that a significant proportion of CTCF mutations are considered oncogenic, the association of mRNA dose with tumour aggressiveness and prognosis is variable, suggesting that the protein is not a tumour suppressor in all contexts." (PMID 30275357, 2018). "R377H and P378L are loss-of-function mutations which abrogate the tumour suppressive effects of CTCF." (PMID 28319062, 2017). "Loss of CTCF PARylation results in epigenetic silencing of certain tumor suppressor genes through destabilization of nearby chromatin boundaries." (PMID 29029387, 2017). "CTCF genetic deletion occurs predominantly in poor prognosis serous subtype tumours, and this genetic deletion is associated with poor overall survival." (PMID 28319062, 2017). "Survival analysis restricted to patients with serous tumours showed that tumours with CTCF copy number loss resulted in reduced overall survival compared to CTCF diploid tumours." (PMID 28319062, 2017). "Studies have suggested that H19 possesses tumor-suppressor functions and have implicated chromatin insulator protein CCCTC-binding factor (CTCF) in methylating the promoter region of the H19 gene." (PMID 26989421, 2016). "It has been postulated that CTCF acts as a tumor suppressive factor, since its function has been associated with altered expression of tumor-suppressor gene, such as E-cadherin, retinoblastostoma, RASSF1A or p16/CDKN2A." (PMID 25352953, 2014). "The experiments above thus indicate that CTCF behaves more like a regulator of other tumor-associated genes than a classical tumor suppressor." (PMID 20119526, 2009).